IL33 (interleukin 33)
Diseases named in the same sentence as IL33 in open-access papers (continued):
Sharing a sentence is not in itself a finding about the gene and the disease.
asthma (continued). "Using inhibitors, it was preciously shown that serine proteases activity from Alternaria induced TSLP and IL-33, potentially playing an important role in the development of allergic inflammation, airway disease, and severe asthma exacerbations." (PMID 30100902, 2018). "In asthma mice model with administration of Alternaria extract, the soluble excretory/secretory products of H. polygyrus suppresses early IL-33 release, Th2 cytokines production by ILCs, as well as eosinophilia." (PMID 29987222, 2018). "The present demonstration of increased lung IL-33 gene expression and protein at viral stimulus-induced exacerbation in WT mice with HDM-induced asthma significantly extends our previous observation on IL-33 expression in this model." (PMID 29361942, 2018). "A study of experimental RV infection in asthma showed that virus-induced IL-33 release correlated with high IL-5 and IL-13 concentrations in the airway." (PMID 30174671, 2018). "In the IL-33-induced asthma model, coadministration of PGE2 or PGE1-alcohol resulted in diminished IL-5 and IL-13 production, reduced eosinophilia and alleviated lung pathology." (PMID 29593738, 2018). "We studied a population of mild to moderate allergic asthmatics, and future studies will need to examine if IL-33 has similar effects across a broader range of asthma phenotypes and degrees of asthma severity." (PMID 30174671, 2018). "An important role of the IL-33/IL-1R4 axis has been proposed in different diseases, such as asthma, inflammatory bowel disease and rheumatoid arthritis." (PMID 29422069, 2018). "pLOF variants in the gene GPR151 protect against obesity and type 2 diabetes, in the gene IL33 against asthma and allergic disease, and in the gene IFIH1 against hypothyroidism." (PMID 29691411, 2018). "We sought to investigate the role of polymerase I and transcript release factor (PTRF) in IL-33 release and asthma pathogenesis." (PMID 29977243, 2018). "Increased serum IL17A and IL33 levels were found in patients with various degrees of asthma as well as steroid-resistant and neutrophilic asthma." (PMID 30306094, 2018). "In premature infant mice following neonatal hyperoxia, IL-33 signaling and ILC2s are also vital for the induction of asthma-like features." (PMID 29987222, 2018). "In people with asthma, IL-33 pre-exposure led to significantly higher RV-induced (in red) IL-5 and IL-13 release (in red) compared to RV alone (in green) (p = 0.02 and p = 0.003 respectively)." (PMID 30174671, 2018). "Since IL-33 can polarize neutrophils, the key regulatory cells in asthma, we found that the eosinophil-activator IL-33 was significantly reduced in the BAL fluid of the 8-day PHF treatment group (p < 0.05)." (PMID 30373169, 2018). "Our study for the first time simultaneously compared the relative balance of membrane bound ST2 and sST2 in asthmatic and healthy individuals, and how this is regulated in vitro by IL-33 and RV in the setting of asthma." (PMID 30174671, 2018). "In contrast to this study, lack of caspase-1 reduced eosinophilia and mature bioactive lung IL-33 levels in an asthma exerbation model." (PMID 30213101, 2018). "TSLP, IL-33, and IL-25 are key mediators of type-2 inflammation diseases (such as asthma, nasal polyposis, and Eosinophilic esophagitis); therefore they are deserving an increasing interest as potential target of new drugs." (PMID 29992143, 2018). "A recent study, involving both experiments in patients and studies using cultured bronchial epithelial cells, has singled out IL-33 as a key mechanistic link between viral infection and exacerbations of asthma." (PMID 29361942, 2018). "The results of studies carried out in the Brazilian population demonstrate a strong relationship between the genetic variants of the gene encoding IL-33 and IL1RL1 with allergy and asthma markers." (PMID 30304837, 2018).
asthma (continued). "Although higher expression of IL-33 has been reported in patients with asthma, it has also been demonstrated in bronchial epithelial cells from those with COPD, especially in a severe stage of COPD." (PMID 29587772, 2018). "Ad5-gsgAM, an adenovirus vector carrying two mycobacterial antigens Ag85A and Mtb32, suppresses Th2 response of asthma by inhibiting IL-33/ST2 axis and favoring Treg expansion in mice." (PMID 29987222, 2018). "It is worth noting that in most cases IL-33 levels demonstrate a correlation with the exacerbation of asthma symptoms." (PMID 30544846, 2018). "Several studies have demonstrated that dysregulation of ST2/IL-33 signaling can promote the pathogenesis of some Th2-related inflammatory diseases such as asthma and allergic inflammation." (PMID 30034292, 2018). "PHF also significantly suppressed pulmonary eosinophilia and asthma-related cytokines IL-4 and IL-33 in bronchoalveolar lavage (BAL) fluid." (PMID 30373169, 2018). "IL-33 is considered to be one of the crucial epithelial-derived cytokines involved in allergic inflammation and asthma development." (PMID 30257479, 2018). "This controlled release of IL-33 eventually prevents the development of asthma exacerbation, and thus PTRF is a potential drug target for future anti-asthma immunotherapy." (PMID 29977243, 2018). "Interleukin 33 has been identified as a trigger of Th2 cell differentiation and engaged in asthma progress." (PMID 29755346, 2018). "Patients with severe asthma have higher mRNA expression of IL-33 on lung tissue compared to controls." (PMID 30386455, 2018). "IL-33 blockade contributes to the alleviation of allergic rhinitis symptoms, and suppresses the development of asthma in mouse models." (PMID 30257479, 2018). "Earlier studies have shown different role of IL-33 in inflammatory diseases; immunosupressive role in obesity, atherosclerosis and experimental fulminant hepatitis and proinflammatory role in asthma and antigen-induced arthritis." (PMID 29988422, 2018). "We identified pLOF variants in IL33 (encoding interleukin 33) and GSDMB (encoding gasdermin B) as associated with a lower risk of asthma." (PMID 29691411, 2018). "Type 2 innate lymphoid cells respond to airway epithelial-derived cytokines, such as IL-25, IL-33 and thymic stromal lymphopoietin, to initiate a type 2 inflammatory event (asthma like) in the respiratory tract." (PMID 29363055, 2018). "The relationship among serum sST2 and IL-33 levels, blood neutrophil counts, and asthma phenotypes should also be evaluated with sputum cell counts in future studies." (PMID 30176857, 2018). "In a metaanalysis, children with asthma were found to have a higher serum level of IL-33 compared to healthy children, though was significant heterogeneity amongst studies." (PMID 30386455, 2018). "Genome-wide association studies (GWASs) have demonstrated that IL-33 and IL1RL1 (encoding the IL-33 receptor) variants were associated with arising asthma and blood eosinophilia." (PMID 30176857, 2018). "IL-33 levels in EBC were increased in COPD patients to a similar extent as in asthma and correlated with blood eosinophil count." (PMID 29859068, 2018). "In contrast, mature IL-33 promotes asthma as well as allergic and anti-parasitic responses through the ST2 receptor and Th2 mechanisms." (PMID 30498500, 2018). "Further, ILC2s are reported to promote asthma at very early age of life through an IL-33-dependent mechanism." (PMID 30105028, 2018). "The genes encoding IL-33 and ST2/IL1RL1 have been identified as major susceptibility loci for human asthma in several genome-wide association studies." (PMID 29977243, 2018). "Although Th2 cells-mediated adaptive immunity is important in asthma process, innate immune mechanisms involving IL-33 are also important in asthma." (PMID 29987222, 2018).
asthma (continued). "While the cytokine IL-33 appears to have pleiotropic functions in diverse types of inflammatory diseases, including inflammatory bowel disease, asthma/allergic diseases, and atherosclerosis, its function in tumorigenesis remains controversial." (PMID 30112116, 2018). "Due to its ability to activate Th2 and dendritic cells, IL-33 plays an important role in initiating allergic inflammation and asthma by producing Th2 cytokines including IL-5 and IL-13." (PMID 29540228, 2018). "Recently, elevated pleural IL-33 and ILC2s were found to mediate the induction of asthma-like responses (e.g., AHR, production of Th2 cytokines) following pdmH1N1 infection in Rag1−/− mice (on a C57Bl/6 background) that lack functional T and B lymphocytes." (PMID 29915592, 2018). "IL-33 is a tissue-derived cytokine that induces and amplifies eosinophilic inflammation and has emerged as a promising new drug target for asthma and allergic disease." (PMID 28273074, 2017). "We have reported that circulating macrophages, as the source of IL-33, contributed to severe asthma." (PMID 28365872, 2017). "IL-33 has emerged as a critical initiator of allergic responses in diseases such as asthma, sparking an array of type 2 reactions in innate lymphoid cells, eosinophils, macrophages, and T cells." (PMID 29045903, 2017). "Proteins associated to asthma and eczema are all related to immunity (IL1ß, IL5, IL33, C-C motif chemokine 5, eotaxin)." (PMID 28598986, 2017). "Higher expression of Th2-driven cytokines (IL-4, IL-5, IL-9, and IL-13), TSLP, IL-25 and IL-33 in nasal tissues was observed in severe asthma." (PMID 28199345, 2017). "There was a strong expression of TSLP, IL-25, and IL-33 in the epithelium, the endothelium of small vessels and subepithelial infiltrating cells in the nasal tissue derived from severe asthma patients with CRS (respectively)." (PMID 28199345, 2017). "An ovalbumin (OVA) asthma model was used in which sensitized C57BL/6 mice were exposed to IL-33 before each OVA challenge." (PMID 28652606, 2017). "Accordingly, common variants in IL1RL1 that associate with increased asthma risk associate with reduced expression of soluble ST2, with the predicted effect being increased IL-33 activity, due to reduced level of this decoy receptor." (PMID 28273074, 2017). "Interleukin 33 (IL-33) represents one of the potential signals from the epithelial cells that trigger the development of asthma." (PMID 28652606, 2017). "Though IL-25 appears to serve a similar function to IL-33, experimental mouse models of asthma have elucidated some important differences." (PMID 28959799, 2017). "In the current study we have taken a new approach where we define the role of IL-33 in exacerbating antigen-induced asthma." (PMID 28652606, 2017). "The higher expression of IL-33/ILC2 axis-directed type 2 immune responses in nasal tissue of CRS brought the greater decline of lung function in severe asthma." (PMID 28199345, 2017). "Here we demonstrate that excess of IL-33 in skin leads to an aggravation of a concomitant OVA-induced asthma-like airway inflammation." (PMID 28490737, 2017). "Association of common sequence variants in IL33 and IL1RL1 with eosinophil counts and asthma in Iceland." (PMID 28273074, 2017). "Given that the skin epithelium is a major source of IL-33, a cytokine that can drive Th2-type responses in both the skin and lung, IL-33 is a likely candidate linking AD and asthma." (PMID 28490737, 2017). "Circulating and tissue levels of IL-33 are increased in experimental models of asthma and blockade of this pathway is able to ameliorate airway inflammation, thereby confirming an in vivo inhibition of IL-33-mediated effects." (PMID 30886947, 2017). "Among susceptibility factors for asthma, the genes IL1RL1/IL18R1, IL33, and TSLP have emerged as some of the most important associated with development of the disease, linking epithelium-derived cytokines to type 2 inflammation." (PMID 28583446, 2017).
asthma (continued). "Applying this analysis to bronchial epithelial cells has revealed SNPs in TSLP, GSDMB, IL33, HLA-DQB1, C11orf30, DEXI, CDHR3, and ZBTB10 that affect asthma risk by allowing cis-regulation of its gene expression in an epithelial specific manner." (PMID 28583446, 2017). "IL-33 has emerged as a critical regulator of several chronic inflammatory diseases, autoimmune diseases and fibrotic disorders including asthma, rheumatoid arthritis, ulcerative colitis, lung fibrosis and cardiovascular disease." (PMID 29263351, 2017). "Its presence in nasal aspirates of human infants with severe RSV, together with the finding that by blocking the receptor of interleukin 33 in vivo, Th2 responses are greatly reduced, suggest it has a role in disease severity and asthma." (PMID 29206851, 2017). "In fact, while this article was under revision, a report demonstrated a casual link between perinatal IL-33 induction and asthma." (PMID 28228256, 2017). "In asthma patients, IL-33 expression was elevated significantly, and in a mouse model of asthma, ST2−/− mice developed attenuated airway inflammation." (PMID 29180837, 2017). "The genes encoding IL-33 and ST2/IL1RL1 have been identified as major susceptibility loci for human asthma in childhood." (PMID 28423665, 2017). "Studies demonstrated that omentin was involved in allergen-induced IL-25 and IL-33 production in asthma." (PMID 29283409, 2017). "IL-33 has been identified as a mediator of various inflammatory diseases such as asthma, cardiovascular diseases, and allergic diseases." (PMID 28484466, 2017). "A severe asthma GWAS identified a novel locus, CDHR3, that had not been observed using broader asthma definitions, in addition to the known asthma susceptibility loci GSDMB, IL33, and IL1RL1." (PMID 28774304, 2017). "In these allergen-induced asthma models, the pulmonary epithelium, macrophages, and DCs release IL-33; in addition, the pulmonary epithelium also produces IL-25, TSLP, and transforming growth factor-β (TGF-β)." (PMID 28271447, 2017). "IL33-induced CXCR2 up-regulation is required for neutrophil activation in a mouse model of asthma mediated by immunoglobulin E." (PMID 28742815, 2017). "Since asthma is characterized by airway hyperresponsiveness (AHR) and altered levels of IL-33 have been associated with asthma, we went further to investigate the effect of IL-33 on AHR in the OVA-induced mouse asthma model." (PMID 28652606, 2017). "In several mouse models of asthma, IL-33 activates lung-resident ILC2s and initiates airway type-2 inflammation." (PMID 28721208, 2017). "Common variants at IL33 and IL1RL1, encoding the IL-33 receptor ST2, associate with eosinophil counts and asthma." (PMID 28273074, 2017). "More recently, we have shown that a specific sub-phenotype of patients with severe asthma and fungal sensitization have even higher levels of IL-33 in both BAL and biopsy." (PMID 28725641, 2017). "IL-33 investigations have been mainly devoted to asthma and allergy, with the development of a targeted IL-33/ST2 axis therapeutic strategy." (PMID 27964756, 2016). "Further, adoptive transfer of dendritic cells pre-treated with IL-33 exacerbated lung inflammation in a DC-driven model of allergic airway inflammation demonstrating the importance of IL-33 in promoting asthma pathogenesis." (PMID 27378934, 2016). "In chronic lung conditions, where OSM is elevated (such as IPF and severe asthma), IL-33 is also upregulated." (PMID 27703303, 2016). "To investigate the anti-asthmatic effects of picroside II, we determined the levels of inflammatory cytokines, such as Th1 cytokine (IFNγ), Th2 cytokines (IL-4, IL-5, and IL-13), and asthma related cytokine (IL-33) in the BALF using ELISA kit." (PMID 27870920, 2016). "For example, an excessive TH2 cells immune response from ST2/IL-33 signaling was found in some type of asthma patients." (PMID 26735493, 2016).
asthma (continued). "The authors state that IL-33 induction directly correlates with viral load and IL-5 and IL-13 levels, proposing IL-33 inhibition as a novel therapeutic approach for virus-induced asthma exacerbations." (PMID 27334012, 2016). "In human, rhinovirus infection induced asthma exacerbation dependent of IL-33 and the production of type 2 cytokines IL-4, IL-5, and IL-13." (PMID 27334012, 2016). "The IL-33/ST2 axis appears to play a pivotal role in some chronic immune inflammatory diseases including asthma, rheumatoid arthritis, and anaphylactic shock." (PMID 27900334, 2016). "Nevertheless, the potential of anti-IL-25 and anti-IL-33 therapeutics to suppress multiple components of the TH2 response responsible for asthma pathogenesis warrants more attention." (PMID 27378934, 2016). "We suggest that this novel model of viral-induced asthma exacerbation has translational value and is suited for in vivo studies involving pharmacological effects on exacerbation-induced expression of IL-33, TSLP and IL-25, as well as PRRs." (PMID 26879906, 2016). "Elevated levels of IL-33 are found in mouse models of allergic airway disease and in chronic human lung conditions including severe asthma." (PMID 27703303, 2016). "There has been much focus recently on the involvement of IL-33 in asthma and this cytokine as a potential therapeutic target." (PMID 26214807, 2015). "IL-33 increases the expression of tryptophan hydroxylase 1, serotonin synthesis, and storage and thus results in airway obstruction in asthma." (PMID 26425339, 2015). "The linkage of viral infection IL33 and Th2 inflammation in the context of asthma has been fostered by a recent publication that described the induction of IL33 in a human experimental model of rhinovirus infection." (PMID 25932636, 2015). "HES has been shown to be protective when administered at sensitization or challenge in the OVA-alum model of asthma 19 and also when administered intranasally with Alternaria extract allergen 20, through suppression of early IL-33 release." (PMID 25867600, 2015). "Different advanced approaches, such as the use of anti-ST2 antibody (clone E310), anti-IL-33 antibody, or soluble ST2-Fc fusion protein have been used to investigate the role of the ST2/IL-33 pathway in asthma models." (PMID 26425339, 2015). "Several studies have shown that IL-33 is expressed more abundantly in asthma patients than healthy individuals." (PMID 26425339, 2015). "It has also been shown that serine proteases released by inflammatory cells play a critical role in the generation of super active forms of IL-33 and enhance immune response in asthma, rheumatoid arthritis, intestinal inflammation and other diseases." (PMID 26425339, 2015). "Both reduced (active) and disulphide bonded (inactive) forms of IL-33 can be detected in lung lavage samples from mice challenged with Alternaria extract and in sputum from patients with moderate–severe asthma." (PMID 26365875, 2015). "In summary, in this study we demonstrate BSMC production of the immunoregulatory cytokine IL-33, which has been forwarded as a potential disease factor in asthma." (PMID 26318341, 2015). "In several clinical and experimental studies IL-33 and its receptor have been found to play important roles in the development of asthma and allergic airway inflammation." (PMID 26214807, 2015). "Identification of IL33 and IL1RL1 as major susceptibility loci in several genome-wide association studies of human asthma suggests that this axis is likely to play an important role in this inflammatory disease." (PMID 26365875, 2015). "IL-25, IL-33 and TSLP have been associated with asthma in a number of investigations, both in the clinic and in animal models, and reduction in their levels should have an important influence on AHR and airway inflammation." (PMID 26214807, 2015). "For example, in murine models of asthma involving sensitization by ovalbumin (OVA) or house dust mite (HDM) the level of IL-33 in lung tissue is elevated." (PMID 26214807, 2015).